FABP4 (fatty acid binding protein 4)
Diseases named in the same sentence as FABP4 in open-access papers (continued):
Sharing a sentence is not in itself a finding about the gene and the disease.
leukemia (11 papers, 2019 to 2025). A malignant (clonal) hematologic disorder, involving hematopoietic stem cells and characterized by the presence of primitive or atypical myeloid or lymphoid cells in the bone marrow and the blood. "Molecular mechanism studies have found high fatty acid-binding protein FABP4 expression in leukemia cells, which competitively consume fatty acids." (PMID 40040719, 2025). "Knocking down FABP4 in vitro or using small-molecule inhibitors significantly inhibits leukemia cell proliferation, and downregulating FABP4 can inhibit leukemia progression and extend mouse survival." (PMID 40040719, 2025). "Adipogenesis, chondrogenesis, and osteogenesis differentiation of BM‐MSCs treated with leukaemia sEVs were determined using FABP4, aggrecan and osteocalcin, respectively." (PMID 38499475, 2024). "In studies of leukemia, AML cells co-cultured with BM adipocytes exhibited higher levels of FABP4, and knockdown of FABP4 prolonged survival in a mouse model of leukemia." (PMID 37065866, 2023). "In leukemia cells, FABP4 regulates DNMT1 expression through the IL-6/STAT3 axis and DNMT1 controls FABP4 through VEGF signaling, thereby forming a mutually reinforcing positive feedback regulation that ultimately promotes AML aggressiveness." (PMID 36106108, 2022). "Furthermore, the lipid chaperone fatty acid binding protein 4 (FABP4) is involved in the interaction of adipocytes with leukemia cells, and its expression correlated with the activation of the peroxisome proliferator-activated receptor (PPAR) γ." (PMID 34012921, 2021). "BM adipocyte-supplied fatty acids are internalized via the leukemia cell scavenger receptor CD36 and transferred to the nucleus by an intracellular lipid chaperone fatty acid-binding protein 4 (FABP4) followed by ligation of PPARγ." (PMID 32133293, 2020). "The FABP4 mRNA level is also increased in AML blasts and a knockdown of FABP4 in a Hoxa9/Meis1-driven murine leukemia model prolongs survival." (PMID 31192118, 2019). "FABP4 inhibition suppresses AML progression and induces leukemia regression in mouse models." (PMID 41048997, 2025). "FABP4 level is also increased in AML cells cultured with BM adipocytes, and knockdown of a lipid chaperone FABP4 prolonged survival of a Hoxa9/Meis1-driven murine leukemia model." (PMID 32133293, 2020).
liver cancer (11 papers, 2018 to 2025). An epithelial or non-epithelial malignant neoplasm that arises from the liver. "FABP4 expression is positively correlated with the degree of steatosis in liver cancer and is associated with an increased risk of postoperative recurrence." (PMID 40717587, 2025). "Previous studies have concluded that high FABP4 expression is associated with poor overall survival in patients with liver cancer." (PMID 36532833, 2022). "Bulk RNA-seq analysis revealed that exogenous FABP4 regulated liver cancer stemness through the PI3K/AKT/β-catenin signaling pathway." (PMID 41392988, 2025). "FABP4 promotes lipid accumulation and proliferation in liver cancer cells through the PPARγ pathway." (PMID 40717587, 2025). "Microsphere formation and clonal formation assays in vitro were applied to study if inhibition of the LPL/FABP4/CPT1 axis can reduce the viability of liver cancer stem cells (LCSCs)." (PMID 34803493, 2021). "Similarly, a previous study demonstrated that inhibition of the LPL/FABP4/CPT1 axis can effectively prevent the progression of NASH to liver cancer." (PMID 38388533, 2024). "However, in alcohol-dependent liver disease, fatty acid binding protein-4 (a protein normally expressed in fat storing cells and white blood cells) is produced by hepatocytes and can stimulate liver cancer growth." (PMID 36358315, 2022). "BMS309403 further reduced liver carcinogenesis in Stelic Animal Model (STAM) mice and reduced the sphere-forming, proliferation, and clonality of liver cancer stem cells, proposing FABP4 inhibition as an emerging therapeutic approach for end-stage liver disease." (PMID 35052876, 2022). "Although activation of the LPL/FABP4/CPT1 metabolic axis may be beneficial for the maintenance of liver cancer stem cells (LCSCs), the genesis of TICs should involve more complex mechanisms that require the malignant transformation of normal hepatocytes." (PMID 34803493, 2021). "FABP4 may promote liver cancer through endothelial cells in NAFLD-HCC." (PMID 37950277, 2023). "Therefore, the synergistic upregulation of the LPL/FABP4/CPT1 molecules in the NASH stage may accelerate the occurrence of liver cancer by nourishing the TICs formation." (PMID 34803493, 2021). "FABP4 upregulates NRF2 and HO-1, reducing ROS accumulation and protecting liver cancer cells from oxidative damage." (PMID 40717587, 2025). "Moreover, the expression levels of PPARα, PPARγ, FABP1, FABP4, and FABP5 were downregulated in GL22-treated xenograft tumors, indicating that GL22 exerted a significant anticancer effect against liver cancer in vivo mediated by PPAR–FABPs signaling pathway." (PMID 29880886, 2018).
rheumatoid arthritis (11 papers, 2020 to 2026). A chronic, systemic autoimmune disorder characterized by inflammation in the synovial membranes and articular surfaces. "Moreover, genes associated with PPAR signaling and rheumatoid arthritis, such as Fabp4 and Ccl2, were also dysregulated, further supporting CLDN17’s role in immune homeostasis and metabolic pathways." (PMID 40332125, 2025). "There are also studies indicating that FABP4 may also promote vascular regeneration in rheumatoid arthritis (RA)." (PMID 41419794, 2025). "The regulation of FABP4 by mTORC1 was also observed in rheumatoid arthritis." (PMID 40090836, 2025). "In this study, we employed bioinformatics and machine learning techniques to identify seven key genes associated with rheumatoid arthritis (RA): AKR1B10, MMP13, FABP4, NCF1, SPP1, COL1A1, and RASGRP1." (PMID 39430588, 2024). "In addition, elevated serum levels of FABP-4 have been reported in chronic inflammatory diseases, such as asthma, rheumatoid arthritis, hypertension, insulin resistance, obesity, cardiac dysfunction, type 2 diabetes, atherosclerosis, acute lung injury, and female stable COPD." (PMID 31905499, 2020). "In patients with rheumatoid arthritis, it has been shown that increased levels of FABP-4 were associated with lipid profiles, independent of the severity of the disease, which indicates the predominant role of FABP-4 in lipid metabolism rather than inflammation pathway." (PMID 31905499, 2020).
stable angina (11 papers, 2012 to 2026). "In the current study, we found that plasma FABP4 levels were independently associated with abnormal QTc interval in patients with stable angina and CKD." (PMID 31234795, 2019). "Using multivariate and trend analyses, a higher concentration of plasma FABP4 level was independently associated with QTc prolongation in patients with stable angina and CKD." (PMID 31234795, 2019). "Therefore, the aim of this study was to investigate whether FABP4 levels were associated with a prolonged QTc interval in a cohort of patients with stable angina and CKD." (PMID 31234795, 2019). "The results of the present study support the idea that FABP4 may act through an inflammation response to play an important role in the pathophysiology of QTc interval prolongation in patients with stable angina and CKD." (PMID 31234795, 2019). "The role of FABP3 and FABP4 as independent predictors of mortality has been reported in subjects with pulmonary embolism and after acute coronary syndrome (ACS), and all-cause death increased together with increasing FABP3 tertiles in subjects with stable angina." (PMID 36978893, 2023). "The results of this study indicated that a prolonged QTc interval in patients with stable angina and CKD was correlated with an elevated FABP4 level." (PMID 31234795, 2019). "We tested blood samples from 50 patients with AMI and 43 patients with stable angina pectoris (sAP) for FGF21, fatty acid binding protein 4 (FABP4), a protein secreted from adipocytes in response to adrenergic lipolytic signal, and total and individual fatty acids." (PMID 31413360, 2019).
cardiac hypertrophy (10 papers, 2016 to 2022). "To identify the mechanisms underlying the FABP4 induced cardiac hypertrophy, we examined those well characterized hypertrophy signal pathways, and our result showed that ERK signaling are strongly induced in FABP4-TG mice heart." (PMID 27294862, 2016). "To gain insight into the molecular signal changes underlying the effect of FABP4 on aggravated cardiac hypertrophy, we examined the activation of MAPK/ERK signaling and PI3K-AKT pathway in heart following pressure overload induced by TAC." (PMID 27294862, 2016). "It is therefore that inhibition of FABP4 in human might show beneficial effects against heart hypertrophy and cardiac events associated with PPARγ agonist drugs." (PMID 27294862, 2016). "Consistently, Lipg deficient were shown to display exacerbated cardiac hypertrophy and HF upon TAC and Fabp4/5 double KO mice were shown to display cardiac hypertrophy." (PMID 35874523, 2022). "High expression of FABP4 promotes the development of cardiac hypertrophy by activating ERK signalling." (PMID 34514716, 2021). "When they were subjected to the transverse aorta constriction (TAC) procedure, the FABP4-TG mice developed more cardiac hypertrophy correlated with significantly increased ERK phosphorylation, compared with wild type controls." (PMID 27294862, 2016). "In conclusion, our data demonstrated for the first time that FABP4 expressed in the cardiomyocytes and can promote cardiac hypertrophy by activating ERK signal." (PMID 27294862, 2016). "The effects of FABP4 on cardiac hypertrophy were investigated in the presence of an ERK signaling inhibitor PD098059." (PMID 27294862, 2016). "Taken together, these results indicated that increased FABP4 levels in cardiomyocytes aggravated the development of cardiac hypertrophy and activated ERK1/2 signaling pathway." (PMID 27294862, 2016). "To identify the molecular mechanism of FABP4 induced cardiac hypertrophy, we performed in vitro studies using primary cultured NRCMs." (PMID 27294862, 2016). "Taken together, these data suggest that the ERK activation is essential for FABP4 induced cardiac hypertrophy." (PMID 27294862, 2016). "It has been reported that FABP4/5 double knockout mice had reduced cardiac contraction due to disturbed utilization of fatty acids in the heart in a model of pressure overload-induced cardiac hypertrophy and failure by transverse aortic constriction." (PMID 33597568, 2021). "In terms of gene expression, transgenic expression of APOB in heart reduces lipotoxic cardiomyopathy in mice, but overexpression of FABP4 in cardiomyocytes aggravates cardiac hypertrophy in mice under pressure overload through activation of extracellular signal-regulated kinase (ERK) signaling." (PMID 30517173, 2018). "We next sought to test whether ERK1/2 signaling activation is required for FABP4 mediated induction of cardiac hypertrophy." (PMID 27294862, 2016). "Thus, we reveal that FABP4 is a positive regulator of cardiac hypertrophy." (PMID 27294862, 2016). "NCRMs were infected with Ad-FABP4 to over-express FABP4 (Ad-GFP as control) and subsequently exposed to cardiac hypertrophy agonist angiotensin II (Ang II)." (PMID 27294862, 2016).
lymph node metastasis (10 papers, 2016 to 2025). "High FABP4 expression is associated with lymph node metastasis and poor prognosis, and a 12-gene model composed of FABP4 and other genes can effectively predict survival." (PMID 40717587, 2025). "Increased FABP4 expression is associated with worse OS and lymph node metastasis, which may be a potential and promising biomarker to assess lymph node status and survival, and may also be a new therapeutic target for patients with node-positive cervical cancer." (PMID 36532833, 2022). "screened 243 genes related to lymph node metastasis in 178 TCGA CC samples and analyzed these genes by univariate and multivariate Cox regression analyses of FABP4 (HR=1.582, P < 0.001) FABP4 (HR=1.384, P=0.024)." (PMID 37056351, 2023). "The expression level of FABP4 was markedly higher in TNM stage III/IV PDAC cases with local invasion and lymph node metastasis than in those without lymph node metastasis, indicating that FABP4 is associated with PDAC carcinogenesis and is likely to be a predictive marker of poor prognosis." (PMID 36060264, 2022). "FABP4 is highly expressed in COAD and correlated with lymph node metastasis, TNM stage and tumor differentiation." (PMID 36203457, 2022). "Our results may indicate that FABP4, GISN2, and CBX7 could be considered predictive biomarkers of the occurrence of lymph node metastases in the cancer of the cervix preoperatively, which could be beneficial in the accurate preoperative design therapy." (PMID 38864083, 2023).
renal dysfunction (10 papers, 2011 to 2025). "Fatty acid-binding protein 4 (FABP4), but not FABP1 (liver-type FABP), is ectopically induced in injured glomerular endothelial cells, and urinary FABP4 (U-FABP4) level is associated with proteinuria and renal dysfunction in a general population." (PMID 33143633, 2020). "There are distinct independent associations of FABP4 level with renal dysfunction, adiposity and high triglycerides level and there is a distinct association of FABP5 level with a low HDL level." (PMID 33071982, 2020). "We previously demonstrated that expression of FABP4 was ectopically induced by glomerular injury in cells of the glomerulus, including glomerular endothelial cells and macrophages, and that the extent of ectopic FABP4 expression was closely associated with proteinuria and renal dysfunction." (PMID 33143633, 2020). "Renal damage manifests as impaired glomerular filtration and increased tubular reabsorption; urinary FABP4 correlates with renal dysfunction and proteinuria." (PMID 41471323, 2025). "Pretreatment with BMS309403, a highly selective inhibitor of FABP4 at a dose of 20 mg kg−1 d−1 for 4 d, significantly reduced serum creatinine levels to improve acute renal dysfunction and attenuated renal tubular damage in injured kidneys." (PMID 35541316, 2018). "FABP4 level was significantly higher in HD patients than in the controls, which is consistent with previous findings in patients with renal dysfunction." (PMID 22102888, 2011). "Serum levels of FABP4 were significantly elevated in mice with ULN plus IRI 10 and 20 min after administration of CL316,243 compared to those in sham-operated group, suggesting that circulating FABP4 levels become more prominent when renal dysfunction and accelerated lipolysis are combined." (PMID 30401801, 2018).
Cirrhosis (9 papers, 2009 to 2025). A chronic disorder of the liver in which liver tissue becomes scarred and is partially replaced by regenerative nodules and fibrotic tissue resulting in loss of liver function. "A recent study discovered that the expression levels of FABP4 and MMP9 can effectively identify patients who are at risk of progressing from MAFLD to MASH, as well as those at risk of advancing from MASH to cirrhosis and HCC, respectively." (PMID 40435176, 2025). "We identified two genes, fatty acid binding protein-4 (FABP4) and matrix metalloproteinase-9 (MMP9), which respectively allowed distinguishing patients at risk of progression from NAFL to NASH and from NASH to cirrhosis and HCC." (PMID 31874999, 2019). "Among all, the top 5 hub genes identified for NAFLD vs. control were CXCL9, NOS2, SERPINE1, FABP4, and LPL, whereas AKR1D1, UGT2B17, CYP26B1, LIPC, and DGAT2 were identified as the top 5 hub genes for the NAFLD vs. cirrhosis group." (PMID 40365443, 2025). "In this study, the expressional levels of SCD2, FABP4 and FABP5 increased during the process from cirrhosis to metastasis in rat model, suggesting that an alteration of the fat metabolism occurred in hepatocarcinogenesis of rat model." (PMID 19638242, 2009). "Additionally, the top 5 biological functional hub genes in NAFLD vs. control (CXCL9, NOS2, SERPINE1, FABP4, and LPL) and NAFLD vs. cirrhosis (AKR1D1, UGT2B17, CYP26B1, LIPC, and DGAT2) groups were identified through PPI analysis among lipid, immune, and metabolism dysregulated genes." (PMID 40365443, 2025). "Interestingly, these results strongly suggested that FABP4 mRNA expression level could help to identify NAFL patients likely to belong to the group of NASH patients and also to identify a subgroup of NASH patients likely to progress to cirrhosis and/or HCC." (PMID 31874999, 2019).
polycystic ovary syndrome (9 papers, 2011 to 2024). A disorder that manifests as multiple cysts on the ovaries. "Thus, data showed that in patients with polycystic ovary syndrome and endometriosis, there was an elevated level of FABP4, which is associated with reduced fertility." (PMID 38731797, 2024). "Elevated circulating FABP4 levels have been found to correlate with impaired reproductive function in women, such as polycystic ovary syndrome and endometriosis." (PMID 37628833, 2023). "It was found that FABP4 is closely related to the occurrence of polycystic ovary syndrome." (PMID 35189817, 2022).
asthma (8 papers, 2011 to 2022). "Interestingly, FABP4-deficient mice were protected from airway inflammation independently of bone marrow-derived elements, indicating possible protection against asthma through FABP action in stromal cells." (PMID 22121495, 2011). "FABP4 expression in bronchial epithelial cells was enhanced by the Th2 cytokines IL-4 and IL-13, which are involved in development of asthma, and was suppressed by the Th1 cytokine interferon γ." (PMID 22121495, 2011). "Additionally, the genes involved in proinflammatory function (ITGB2 and FABP4) and apoptosis process (IFI27) were elevated in asthma." (PMID 36439114, 2022).
Glucose intolerance (8 papers, 2011 to 2023). Glucose intolerance (GI) can be defined as dysglycemia that comprises both prediabetes and diabetes. "Crif1f/+,Fabp4 mice fed a HFD for 14 weeks showed more advanced glucose intolerance, with higher basal (168.8±13.2 mg/dL vs 131.3±8 mg/dL) and peak (516.8±34.8 mg/dL vs 420.4±52.3 mg/dL) plasma glucose levels." (PMID 23516375, 2013). "More impressively, Crif1f/+,Fabp4 mice fed a HFD for 8 weeks showed an earlier onset of glucose intolerance, which was characterized by higher peak glucose levels than those measured in control mice in the intraperitoneal glucose tolerance tests." (PMID 23516375, 2013). "Similar to Crif1f/+,Fabp4 mice, Crif1f/f,Adipoq mice developed glucose intolerance even in being fed a NCD, at 8 weeks-of-age." (PMID 23516375, 2013). "This indicates that insulin signaling in adipose tissue may not be the principal cause of the systemic glucose intolerance of Crif1f/+,Fabp4 mice." (PMID 23516375, 2013). "However, Crif1f/+,Fabp4 mice fed a NCD for 14 weeks developed glucose intolerance." (PMID 23516375, 2013).